PRSS56 (serine protease 56)
Diseases named in the same sentence as PRSS56 in open-access papers (continued):
Sharing a sentence is not in itself a finding about the gene and the disease.
neurofibroma (1 paper, 2025). An intraneural or extraneural neoplasm arising from nerve tissues and neural sheaths. "We explored the Prss56-Nf1 knockout (KO) mouse model that recapitulates neurofibromas and pseudarthrosis by carrying Nf1 gene inactivation in Prss56-expressing boundary cap cells, a neural crest subset, and their derivatives." (PMID 41397954, 2025).
scoliosis (1 paper, 2025). A congenital or acquired spinal deformity characterized by lateral curvature of the spine. "Combined treatment with selumetinib and RMC-4550 effectively prevented scoliosis in Prss56-Nf1fl/- mice while 33.3% (5/15) and 50% (7/14) of vehicle-treated mice developed scoliosis by 12 and 16 months, respectively." (PMID 41397954, 2025). "Scoliosis was identified in 18.6% (8/43) and 30.77% (12/39) of Prss56-Nf1fl/fl and 33.30% (7/21) and 27.8% (8/29) of Prss56-Nf1fl/- mutant mice at 12 and 14-20 months of age, respectively." (PMID 41397954, 2025). "We also identified Prss56-Nf1 mutant mice with scoliosis and high kyphosis angle (above 80°) recapitulating NF1 kyphoscoliosis spine deformity from 12 months of age." (PMID 41397954, 2025). "No scoliosis was detected in Prss56-Nf1+/+ control mice from 3 to 20 months of age." (PMID 41397954, 2025).
cancer (3 papers, 2023 to 2025). A tumor composed of atypical neoplastic, often pleomorphic cells that invade other tissues. "By extension, the overexpression of PRSS56 in other cancers may also be caused by the hypomethylation of its promoter DNA." (PMID 37400936, 2023). "We identified 30 cancer-specific normal-invariant genes, including Zic family members (ZIC1, ZIC4, and ZIC5), DPPA2, PRSS56, ELF5, and FGF18, most of which were cancer-associated genes." (PMID 39969322, 2024). "In this study, we identified PRSS56 as a novel CT antigen that is frequently overexpressed in cancers, especially in GIC." (PMID 37400936, 2023). "In summary, PRSS56 was identified as a novel cancer-testis antigen, which is overexpressed in numerous cancers, especially gastrointestinal cancers." (PMID 37400936, 2023). "Our results presented here represent the first data on the function of the serine protease PRSS56 in cancers." (PMID 37400936, 2023). "The CT antigen PRSS56 is frequently overexpressed in cancers, especially in gastrointestinal cancer." (PMID 37400936, 2023). "Serine protease PRSS56 is a novel CT antigen that is reactivated in cancers by promoter DNA hypomethylation." (PMID 37400936, 2023). "In order to explore the potential molecular mechanism of PRSS56 driving cancer progression, we compared the transcriptome differences between four patients with high PRSS56 expression and four patients with low PRSS56 expression in the TCGA_STAD cohort." (PMID 37400936, 2023). "The pan-cancer analysis showed that PRSS56 expression was significantly upregulated in various cancers, especially GC and CRC." (PMID 37400936, 2023). "PRSS56 was frequently overexpressed in various cancers, especially in gastrointestinal cancer." (PMID 37400936, 2023). "Notably, our results presented here represent the first data on the function of the PRSS56 in human cancer." (PMID 37400936, 2023). "Importantly, our finding suggested the overexpression of PRSS56 in cancers is probably due to its promoter DNA hypomethylation." (PMID 37400936, 2023). "The role of serine protease PRSS56 in cancers remains unknown to date." (PMID 37400936, 2023). "In addition, we also analyzed the frequency of PRSS56 overexpression in pan-cancer." (PMID 37400936, 2023). "However, the biological function of serine protease PRSS56 in cancers remains unknown to date." (PMID 37400936, 2023). "However, the biological function of PRSS56 in cancers remains unknown." (PMID 37400936, 2023). "Thus, in order to further confirm whether PRSS56 is a CT gene or not, RNA sequencing studies were performed in human cancer cell lines after exposure to the well-known DNA methyltransferase inhibitor (5-AZA-CdR)." (PMID 37400936, 2023).
tumor (3 papers, 2023 to 2025). "Since Prss56 reactivation did not occur during pNF development and malignant progression, all Tom+ tumor SCs were considered originating from BC cells." (PMID 41223283, 2025).
neurological disorders (1 paper, 2017). "In this cohort, seven genes have already been associated with neurological disorders (MNX1, NINJ1, PER2, PHF20, PRSS56, RPH3A, and SBF1) in MalaCards and OMIM." (PMID 28769055, 2017).
PRSS56 also shares sentences with these, for which no sentence is quoted: angle-closure glaucoma (2 papers); liver cancer (2); congenital cataract (1); ectopia lentis (1); esophagus cancer (1); Leber congenital amaurosis (1); Marfan syndrome (1); plexiform neurofibroma (1); rectal cancer (1); retinitis pigmentosa (1); retinoschisis (1); stomach cancer (1).